ATAD2 (ATPase family AAA domain containing 2)
Diseases named in the same sentence as ATAD2 in open-access papers (continued):
Sharing a sentence is not in itself a finding about the gene and the disease.
cancer (continued). "Our previous investigation of ATAD2/Atad2 gene expression pattern and protein accumulation showed that the gene is normally highly expressed in male germ cells and that it is also frequently abnormally active in many cancers, similar to many other testis-specific genes." (PMID 26459632, 2016). "Additionally, we found that HCC cells with ATAD2 suppression also showed reduced stress fiber formation, as detected by phalloidin staining, suggesting that ATAD2 may participate in cytoskeletal reorganization of cancer cells." (PMID 26497681, 2015). "Thus, ATAD2 manifests oncogenic function and plays a significant role in cancer development." (PMID 26697062, 2015). "However, the molecular mechanisms by which ATAD2 regulates cancer cell proliferation and invasion remain unclear." (PMID 24552534, 2014). "Computational analysis initially identified 40 cancer-active CTA genes, of which four genes (LY6K, MAGEA3, CEP55, and ATAD2) were most indicative of nodal spread." (PMID 41009820, 2025). "ATAD2 belongs to the family IV bromodomain-containing (BRD) protein and is a cancer-testis antigen (CTA) localized to the nucleoplasm." (PMID 41154392, 2025). "ATAD2 expression can be regulated by the oncogenic E2F transcription factor and in turn binds and activates the MYC transcription factor, thus driving cancer progression." (PMID 38596293, 2024). "ATAD2, BRMS1L, PUF60, SHQ1, and USP4 were found to influence overall survival in 15, 9, 13, 13, and 12 of the 21 cancer types, respectively." (PMID 39127727, 2024). "Upon estrogen stimulation, ATAD2 is selectively recruited to the promoters of ERα target genes, such as cyclin D1, c-Myc and E2F1, which are required for estrogen-induced cancer cell proliferation." (PMID 36632213, 2023). "In a variety of types of malignant tumors, there is a consistent over-expression of multiple BCPs genes on which tumors depend, including BRD2, BRD4, ATAD2, KAT2A, etc.." (PMID 37142850, 2023). "ATPase family AAA domain-containing protein 2 (ATAD2) has ATP binding and ATP hydrolysis activity and it is highly expressed in various cancers, including CRC." (PMID 37644393, 2023). "ATAD2, also known as ACNNA, has a chromosomal location of 8q24.13, which is a commonly amplified region in cancer." (PMID 36008934, 2022). "The development of novel inhibitors selectively targeting the ATAD2 and ATAD2B bromodomains has been essential in identifying new functions for these proteins, and their contributions to cancer development." (PMID 34298819, 2021). "A similar observation was made for deep CNAs in ERGs, namely BOP1 (four cancers), ATAD2 (four cancers), MECOM (three cancers), and PHF20L1 (three cancers)." (PMID 32963031, 2020). "Mechanistically, ATAD2 can regulate multiple oncogenes, such as c-Μyc, E2F1 and cyclin D1, which are capable of contributing to cancer cells survival via enhancing cell proliferation, invasion and migration." (PMID 32174193, 2020). "Among the recurrent genomic events, those in BRD9, EP300, ATAD2, HDAC4, PRBM1, BRD4, and BRD1 were observed in the highest numbers of cancer types (nine, eight, eight, eight, seven, seven, and seven, respectively)." (PMID 30760718, 2019). "Markedly, the CTA genes ATAD2, CEP55, FANCA, KIF2C, NUF2, OIP5, and PBK had significantly positive expression correlations with the PLK1 expression in 30 cancer types (Pearson correlation, FDR<0.1)." (PMID 30631355, 2018). "Many regulators including CBP/p300, ATAD2, Cyclin E2, SWI/SNF and NPAT play important roles in cancer survival and proliferation." (PMID 29212286, 2017). "This is interesting, since links between ATAD2, B-MYB and E2Fs has been reported also in other cancers." (PMID 26308378, 2015). "Taken together, our data suggest that ATAD2 is a clinically and biologically relevant therapeutic target in HCC which is amenable to the development of effective anti-cancer approaches." (PMID 26497681, 2015).
cancer (continued). "Previous studies indicated that ATAD2 directly interacted with the oncogene AIB1/ACTR and played an important role in the recruitment of ERα to promote the expression of genes driving cancer cell proliferation." (PMID 26697062, 2015). "We identify copy number gain of ATAD2 as a regulator of ATAD2 expression, present the first data linking ATAD2 overexpression to MYC activation, and provide functional data suggesting ATAD2 as a therapeutic target in MYC-dependent cancers." (PMID 23393560, 2013). "Twenty of these genes are located in 8q22–q24 and 17q21, including PAPBC1, RAD21, ATAD2, MTSS1, SQLE, ST3GAL1, C17orf37, ABCC3 and PTPN2, previously reported as cancer-related genes." (PMID 21339811, 2011). "Survival analysis showed that several of the dysregulated genes (e.g. ATAD2, BRMS1L, PUF60, SHQ1, and USP4) have an impact on prognosis in multiple cancer types, thereby further highlighting the clinical significance of aberrant gene expression patterns on patient survival." (PMID 39127727, 2024). "For instance, human ATAD2 (ATPase family AAA+ domain-containing protein 2) has been described as a transcriptional coactivator for chromatin modifications and is found upregulated in a wide range of cancers." (PMID 37626962, 2023). "Also, ATAD2 interacts with Myc, E2F, and SOX10 transcription factors facilitating cancer progression." (PMID 36674511, 2023). "Together, ATAD2 acts as a transcriptional co-activator of ER and AR, regulating the expression of ER/AR-targeted genes to control cancer cell proliferation and survival 84, even without gonadal hormone stimulation." (PMID 36632213, 2023). "Using clinicopathologic data, we demonstrated that higher‐grade tumors display significant upregulation of ATAD2 and SMARCA4 expression, and downregulation of SMARCA2 expression, which further confirms a universal relation of these BrD proteins' expression with cancer stemness." (PMID 35049055, 2022). "Although the current research has made some progress, the main mechanism of ATAD2 is not the same for different types of malignant tumors." (PMID 36008934, 2022). "ATAD2 positively regulates the oncogene AIB1/ACTR expression, and serves as a transcriptional co-regulator for AR and ERα, resulting in elevating the expression of genes that promote cancer cell proliferation and survival." (PMID 32174193, 2020). "For example, 66.7% (42/63) of putative therapeutic target HAMPs are largely uncharacterized with limited indications about how these genes influence cell biology and cancer, although many of these understudied HAMPs are recurrently altered among cancers, such as BRD9, BRD1, BPTF, and ATAD2." (PMID 30760718, 2019). "The oncogene ATAD2 is a member of the AAA+ ATPase family of proteins that contains both a bromodomain and an ATPase domain, and the gene maps to chromosome 8q24 in a region that is frequently amplified in cancer." (PMID 25880458, 2015). "This may account for some of the effectiveness of HDAC inhibitors as cancer therapeutics, and we found cell lines that were sensitive to knockdown of MYC or ATAD2 were also sensitive to the HDAC inhibitor Trichostatin-A." (PMID 23393560, 2013). "ATAD2 is a non-canonical ATP-dependent histone chaperone and a major cancer target." (PMID 37770645, 2023). "The exact function of the human Abo1 homologue ATAD2 in both cancer and non-cancer cells remains unclear." (PMID 32269268, 2020). "However, we did not observed any differential expression of ATAD2 mRNA among different races or family cancer histories." (PMID 32462022, 2020).
cancer (continued). "However, despite strong evidence for a functional implication of Atad2 in DNA replication, in neither cancer cells nor exponentially growing ES cells, the absence of Atad2 affected cell growth." (PMID 26459632, 2016). "Finally, we found that downexpression of ATAD2 could dramatically suppress the proliferation of SW480 and HCT116 cells, which is in keeping with the previous studies on the other cancer cells." (PMID 26697062, 2015). "ATAD2 (ATPase family AAA domain-containing protein 2), a member of the AAA + ATPase family of proteins, was identified by microarray analysis, contains both a bromodomain and an ATPase domain, and maps to chromosome 8q24 in a region that is frequently amplified in cancer." (PMID 24552534, 2014). "ATAD2 expression was higher in non-endometrioid, high-grade and ER negative tumors (p<0.001, p<0.001, and p = 0.02 respectively); high MYC signaling was associated with poorly differentiated (p = 0.0016) and non-endometrioid (p<0.001) cancers." (PMID 23393560, 2013). "In addition to this conclusion, our finding that the forced expression of ATAD2 increases the sensitivity of hypoxic cancer cells to anticancer drugs justifies the development of a novel strategy to inhibit the reduction in ATAD2 protein to sensitize hypoxic tumor cells to chemotherapy." (PMID 38730681, 2024). "Therefore, it is not difficult to speculate that in cancer with negative or positive gonadal hormone receptors, ATAD2 may both have strong potential targeting value." (PMID 36632213, 2023). "Among other discoveries, this work showed that in the absence of ATAD2, HIRA becomes trapped on chromatin leading to its accumulation in ES cells, as well as in a variety of cancer cell lines." (PMID 41557467, 2026).
tumor (45 papers, 2014 to 2026). "Because the Warburg effect plays a critical role in promoting tumor growth, our data further support that ATAD2 has a huge potential to function as a therapeutic target for treating ccRCC." (PMID 37233956, 2023). "As a member of the ATPase family, the ATPase family AAA domain-containing protein 2 (ATAD2) is recently reported to be closely associated with tumor progression." (PMID 37233956, 2023). "Among the 486 co-upregulated genes, ATAD2 is recently reported to be closely associated with tumor progression; however, its role in ccRCC remains elusive." (PMID 37233956, 2023). "ATAD2 overexpression is associated with histological grade, tumor metastasis, and poor survival in BC, and it is a potential drug therapy target." (PMID 36008934, 2022). "The overexpression of ATAD2 in various human malignancies causes the imbalance in proliferation and apoptosis of tumor cells leading to tumor development." (PMID 36008934, 2022). "ATAD2 is not only tumorigenic but also associated with immune cell infiltration in the tumor microenvironment in osteosarcoma (OS)." (PMID 36008934, 2022). "It is currently believed that high ATAD2 expression is associated with high histological grade, low overall survival, and tumor metastasis and recurrence in a variety of malignancies, but the ATAD2 oncogenic signaling pathway has not been fully clarified." (PMID 36008934, 2022). "Clinicopathological analysis indicated that the overexpression of ATAD2 was associated with tumor size in PTC tissues." (PMID 29515109, 2018). "In this study, the relationship between ATAD2 and immune lymphocyte infiltration was evaluated using the bioinformatics database, which showed that ATAD2 is not only associated with angiogenesis but also with tumor immune infiltration." (PMID 36479043, 2022). "Moreover, ATAD2 overexpression rescued the inhibition of tumor growth caused by miR-302 in xenograft mice." (PMID 36139505, 2022). "To investigate whether ATAD2 expression regulated by miR-302 is associated with tumor growth in vivo, we implanted the Mock, miR-302, or miR-302/ATAD2 expressing SKBR3 and T47D cells subcutaneously into nude mice." (PMID 36139505, 2022). "Furthermore, univariate analysis showed that elevated ATAD2 expression was significantly associated with the OS of CRC patients; multivariate analysis demonstrated that ATAD2 expression, tumor size, and clinical stage are independent risk factors for the prognosis of CRC patients." (PMID 26697062, 2015). "As a transcription factor co-activator, ATAD2 partners with various factors, including the androgen receptor, E2Fs, and c-Myc, to facilitate tumor progression." (PMID 41158756, 2026). "The knockdown of ATAD2 led to a decrease in subcutaneous tumor size and weight, a reduction in Ki67 expression, and an extension of survival in mice bearing intracranial in situ tumors." (PMID 41158756, 2026). "ATAD2 also facilitates immune suppression through interactions with inhibitory immune checkpoints and tumor-infiltrating cells." (PMID 41154392, 2025). "By contrast, normal epithelial cells located adjacent to tumor cells lost ATAD2 expression, supporting the notion that these cells had undergone differentiation and consequently lost their stem cell characteristics." (PMID 40050746, 2025). "Although several potent and selective ATAD2 inhibitors have been reported, most lack appreciable cellular activity and druggability, especially in inhibiting tumour growth, which limits the clinical application of ATAD2 inhibitors." (PMID 37533352, 2023). "Pharmaceutical giant Bayer has also made significant efforts to develop novel ATAD2 inhibitors as innovative anti-tumor drugs." (PMID 36632213, 2023). "Despite considerable interest in identifying ATAD2-targeted drugs, surprisingly little is known about the cellular functions of ATAD2 and the mechanism of tumor malignancy." (PMID 37770645, 2023).
tumor (continued). "An increasing body of evidence suggests that ATAD2 promotes cell proliferation and metastasis in tumor occurrence and development." (PMID 37233956, 2023). "Accumulating evidence has revealed that ATAD2 is involved in the carcinogenesis, proliferation, apoptosis and metastasis of various tumor cells." (PMID 36632213, 2023). "We first examined the mRNA expression of ATAD2 in 33 breast normal/tumor tissue pairs via RT-PCR analysis." (PMID 36139505, 2022). "Specifically, ATAD2 exhibit the highest level of aberrations that accounts for 10% of all profiled samples (10 506 samples in 27 solid TCGA tumor types)." (PMID 35049055, 2022). "ATAD2 has received extensive attention in recent years as one prospective oncogene with tumor-promoting features in many malignancies." (PMID 36008934, 2022). "ATAD2 is a very promising tumor-promoting factor, and it is necessary to study its function in tumors." (PMID 36008934, 2022). "ATAD2 overexpression is correlated with the clinical stage, depth of tumor invasion, lymph node, and distant metastasis of GC and is an independent factor in the prognosis of GC patients." (PMID 36008934, 2022). "The effects of ATAD2 on UCEC tumor growth and angiogenesis were verified with in vivo and in vitro correlation experiments." (PMID 36479043, 2022). "It was also found that ATAD2 overexpression in other types of malignancies has multiple pro-tumor proliferation and survival roles." (PMID 36008934, 2022). "As expected, we also detected a robust enrichment of ATAD2‐associated and TRIM28‐associated gene expression profiles with stemness signatures across most TCGA tumor types." (PMID 35049055, 2022). "Overexpression of ATAD2 and PVT1 in 8q24.13, RAD54B, LAPTM4B, and RRS1 in 8q21.13 were reported to be associated with tumor proliferation and progression of HCC." (PMID 36010950, 2022). "Here, we demonstrate that ATAD2 upregulation positively correlates with a higher tumor grade of HNSC, KIRC, LGG, LIHC, OV, PAAD and UCEC tumors, and higher‐grade tumors clearly display stem cell features, particularly stemness‐related gene expression profiles." (PMID 35049055, 2022). "Immunohistochemical experiments were subsequently performed on the embedded wax blocks of transplanted tumors to further confirm the relationship between ATAD2 and tumor angiogenesis at the tissue level." (PMID 36479043, 2022). "The associations of ATAD2 and KIF4A with ESCC patient clinical outcome were analyzed, including age, gender, tumor size, tumor differentiation, and distant lymph node metastasis." (PMID 36046597, 2022). "We then investigated the effect of ATAD2 on tumor metastasis through in vitro transwell assay and in vivo murine lung metastatic model." (PMID 33757572, 2021). "To elucidate the molecular mechanism of ATAD2 in promoting tumor metastasis in ESCC, we performed RNA sequencing on KYSE510 cells infected with two validated shRNAs targeting ATAD2 and a control shRNA." (PMID 33757572, 2021). "We discovered TGF-β signaling pathway listed on the top one of the pathways associated with ATAD2 via RNA-sequencing and proved the regulation role of ATAD2 on TGF-β1, which clarified a tumor-promoting role of TGF-β signaling pathway in ESCC." (PMID 33757572, 2021). "Consistent with in vitro assays, tumor growth was significantly decreased in ATAD2 knockdown group compared with control group (P < 0.01), and the group with ectopic expression of ATAD2 grew larger tumors compared with the ATAD2 knockdown group (P < 0.05)." (PMID 33757572, 2021). "The high levels of ATAD2 protein were correlated with tumor size (P = 0.018), metastasis (P = 0.009), serum alpha-fetoprotein (AFP) (P = 0.010), and TNM stage (P = 0.033)." (PMID 32462022, 2020). "Our findings showed that through small RNA interference targeting ATAD2, tumor cell proliferation was inhibited and apoptosis and G1 cell cycle arrest were induced." (PMID 32669963, 2020).